INS (insulin)
Diseases named in the same sentence as INS in open-access papers (continued):
Sharing a sentence is not in itself a finding about the gene and the disease.
Insulin resistance (continued). "Vitamin D deficiency in T2DM patients might impair insulin secretion leading to abnormal glucose metabolism and insulin resistance." (PMID 37072813, 2023). "This decrease in whole-body insulin-mediated glucose uptake and the associated insulin resistance can cause persistent muscle loss, and may even be a factor in the development of MAFLD." (PMID 38024359, 2023). "ZFYVE28 may be a potential therapeutic target to improve insulin sensitivity and prevent metabolic and cardiovascular diseases associated with insulin resistance." (PMID 37884540, 2023). "Therefore, it is necessary to update the physiology of insulin signaling and the disordered physiological processes associated with insulin resistance, henceforth proposing more effective therapies for treating diseases related to insulin resistance." (PMID 37664840, 2023). "High fat diet–induced insulin resistance was aggravated and reversed by hepatocyte-specific Usp4 deficiency and Usp4 overexpression, respectively, as assessed by fasting insulin levels, homeostasis model assessment-insulin resistance (HOMA-IR), glucose tolerance tests, and insulin tolerance tests." (PMID 36834633, 2023). "Our results may be explained by the evolution of insulin resistance in birds which selected for loss or downregulation of genes related to insulin-mediated glucose import in cells." (PMID 37577544, 2023). "Furthermore, obesity causes a state of insulin resistance, there is increased insulin and insulin-dependent growth factors." (PMID 37370811, 2023). "In addition, our study showed that higher concentrations of vitamin D were significantly linked to lower glucose & insulin concentrations, and Homeostatic Model Assessment for Insulin Resistance (HOMA-IR)." (PMID 36833019, 2023). "High glycemic index and glycemic load diets are associated with cancer development and worse prognosis, partially explained by the adverse effects on insulin metabolism, causing hyperinsulinemia and insulin resistance, and also by inflammation and oxidative stress induction." (PMID 37686842, 2023). "Firstly, excess PTH may disturb the ability of the beta cells to improve insulin secretion appropriately, causing insulin resistance through a calcium-dependent mechanism." (PMID 37051200, 2023). "T2D is additionally associated with a prolonged increase in blood glucose levels, which may have two causes: deficiencies in insulin secretion due to impairment of β-cell function or that of its receptor (insulin resistance)." (PMID 38069300, 2023). "Therefore, the supplementation of vitamin D reduces the risk of insulin resistance and circulating levels of insulin; the inverse correlation between vitamin D and HOMA-IR becomes more robust with increasing Body Mass Index (BMI)." (PMID 37895163, 2023). "Propionate may cause glycogenolysis, insulin resistance, and hyperglycemia by increasing plasma levels of glucagon, insulin counter-regulatory hormones, and fatty acid-binding protein 4 (FABP4) in both mice and humans." (PMID 37432305, 2023). "In essence, during over-nutrition states, a shift in redox status is implicated in insulin resistance and this results in impaired response to insulin in the skeletal/cardiac muscle and hepatic tissues with the characteristic dysfunctional control of glucose uptake and uncontrolled gluconeogenesis." (PMID 36670985, 2023). "However, elevated levels have been linked to insulin resistance, lower insulin secretion, and a higher risk of developing T2D." (PMID 38132860, 2023). "Moreover, in the PLIS study, 908 individuals with prediabetes were stratified into low-risk or high-risk phenotypes based on insulin secretion, insulin resistance, and liver fat content." (PMID 37836486, 2023). "Furthermore, in physiology, excess free fatty acid (FFA) delivery to insulin-sensitive tissues while fasting competes with glucose and causes insulin resistance, whereas treatment with SGLT2i is associated with improved insulin sensitivity." (PMID 36809274, 2023).
Insulin resistance (continued). "In addition, insulin secretion during intraperitoneal glucose tolerance tests was attenuated in apoM-KO mice, indicating that apoM deficiency exacerbated insulin resistance during HFD." (PMID 37628901, 2023). "Moreover, in girls, there is an inverse association between adiponectin levels and insulin concentration as well as the homeostasis model assessment of insulin resistance (HOMA-IR)." (PMID 38004353, 2023). "According to the literature, the administration of L-arginine as an individual supplement or in combined therapy stimulates insulin sensitivity (considering that NO production is strictly associated with insulin resistance) and affects glucose and insulin homeostasis." (PMID 38004508, 2023). "Previous studies suggest that increased levels of interleukin-6 (IL-6) and TNF-α may be linked to obesity and insulin resistance, signifying their involvement in ER stress and reduced insulin sensitivity." (PMID 38140341, 2023). "Obesity and insulin resistance are both causal factors for hypertension, as insulin resistance and increased insulin levels have been linked to reduced release of nitric oxide, and activation of the renin-angiotensin pathway, causing blood vessel constriction and consequently high blood pressure." (PMID 37351191, 2023). "DM may be characterized as type 1—autoimmune destruction of beta-islet pancreatic cells that produce insulin—or type 2, which is associated with tissue insulin resistance, central obesity, dysregulated adiposity, and eventual insulin production deficits." (PMID 37829606, 2023). "The mechanism may be related to insulin resistance in the myocardium, and the expression of insulin-dependent GLUT-4 is more susceptible to environmental factors." (PMID 37005683, 2023). "As observed in adult models, animals exposed to maternal glycation do not develop insulin resistance, glucose dysmetabolism, or changes in insulinemia, although a lower kITT indicates an insufficiency in insulin action, suggesting a predisposition to insulin resistance." (PMID 36904281, 2023). "Burn injury stimulates insulin production and produces insulin resistance in liver, skeletal muscle, and adipose tissue, associated with post-receptor alterations such as phosphorylation of the insulin receptor substrate-1 (IRS-1) in the absence of changes in insulin receptor binding." (PMID 37333522, 2023). "TMEM173, hsa-miR (-611 and -1976) and RP4-605O3.4 showed a significant difference in their expression, which makes the use of these insulin resistance associated biomarkers together with HOMA-IR possible in differentiating insulin resistant from insulin sensitive patients." (PMID 37223012, 2023). "Although it has been documented that patients with high IA levels may present with a rare syndrome of severe insulin resistance (requiring more than 200 U/d of insulin for at least two days), the underlying causal mechanism remains unclear." (PMID 37143729, 2023). "Night eating was associated with higher HbA1c, insulin resistance, insulin, and HDL." (PMID 36771469, 2023). "Hypovitaminosis D might also cause insulin resistance, and adequate vitamin D supplementation is demonstrated to improve insulin receptivity." (PMID 36839456, 2023). "Furthermore, long-term exposure to elevated FFAs and increased hepatic triglyceride and glucose synthesis synergistically cause damage to the β-cells of the pancreas and impair insulin secretion, contributing to the development of insulin resistance and T2DM." (PMID 37424869, 2023). "A recent study including proteomics of potential insulin resistance biomarkers in PCOS women showed that only ApoC3 was flagged as potentially being a diagnostic marker for PCOS-insulin-resistant subjects; however, in this study, ApoC3 was not available in the Somascan panel." (PMID 36980195, 2023).
Insulin resistance (continued). "One of the main characteristics of MetS is insulin resistance, a condition that is present in more than 80% of the patients and that is associated with impaired insulin sensitivity in insulin-dependent tissues such as the liver, adipose tissue and the skeletal muscle." (PMID 37239868, 2023). "Another possibility to consider, although not demonstrated by the present data, is that weight loss mediated by dapagliflozin might decrease insulin resistance and increase the effect of the administered insulin." (PMID 37954838, 2023). "Insulin resistance and compensatory hyperinsulinemia might be important contributors to hypertension through several mechanism including loss of insulin-induced vasodilation, activation of sympathetic nervous system and increased renal sodium reabsorption." (PMID 37833676, 2023). "Mitochondrial dysfunction plays a causal role by governing insulin secretion failure in β-cells and peripheral insulin resistance through the gluco-lipotoxicity or by impairing the regulation of glucose homeostasis in neurons of different cerebral regions and glial cells in the brain." (PMID 37174622, 2023). "For obese individuals at risk of insulin resistance, most clinics recommend a TG concentration of 1.47 mmol/L (130 mg/dL) or TG/HDL-C (>3), and insulin concentrations (109 pmol/L) to help identify insulin resistance and increase the risk for various adverse outcomes." (PMID 37818160, 2023). "Further, impaired mitochondrial DNA synthesis caused by vitamin B12 deficiency or high folate may lead to insulin resistance by triggering impaired insulin signaling through mitochondrial stress, thus leading to GDM." (PMID 37375669, 2023). "In addition, accumulating evidence suggests that oxidative stress is involved in the development of insulin resistance in animal models, which verifies the association between dysregulated glutathione metabolism and impaired insulin action in fat cells." (PMID 36823659, 2023). "A possible explanation for the discrepancy between our results and the earlier findings is that in participants with type 2 diabetes and insulin-resistant offspring of type 2 diabetics, the pathogenesis of insulin resistance is probably linked to heritable defects of mitochondrial metabolism." (PMID 37210569, 2023). "We identify gut bacteria associated with insulin resistance and insulin sensitivity that show a distinct pattern of carbohydrate metabolism, and demonstrate that insulin-sensitivity-associated bacteria ameliorate host phenotypes of insulin resistance in a mouse model." (PMID 37648852, 2023). "Deficient INSR gene processing may impair insulin biological responses, ultimately causing insulin resistance and glucose intolerance." (PMID 37894381, 2023). "Indeed, insulin resistance, impaired insulin signaling and obesity associate with more severe adipose tissue dysfunction, inflammation, MVD and decreases in cardiac efficiency in women than men." (PMID 37658327, 2023). "Because obese individuals are in a high-fat state, the increase of free fatty acid content in this state causes insulin resistance and reduces the number of pancreatic β-cells by apoptosis, leading to abnormal insulin secretion and decreased expression of insulin-receptor-related proteins." (PMID 37107215, 2023). "It has recently been shown that in excess weight insulin-resistant subjects reduction of dietary sodium improves cardiac function, and this effect may be associated with improvement in insulin resistance." (PMID 36984767, 2023). "However, an increasing number of (prospective) human studies suggests an alternative scenario: in this scenario, chronic hypersecretion of insulin is the primary abnormality leading to hyperinsulinemia and precedes, initiates, and causes insulin resistance." (PMID 36901984, 2023). "It has been reported that high insulin levels and insulin resistance may be associated with the emergence and development of hyperuricemia in obese individuals." (PMID 37761454, 2023).
Insulin resistance (continued). "Associations of various adipokines with not only insulin resistance but also with increased insulin sensitivity, increased systolic blood pressure, and atherosclerosis highlight the significance of adipokines in several components of metabolic syndrome and metabolic diseases in general." (PMID 37239090, 2023). "Moreover, the congenic study clarified that Nidd5nsy harbors a locus that causes hyperglycemia, insulin resistance, insufficient insulin secretion to compensate for insulin resistance, and visceral obesity." (PMID 36693911, 2023). "T2DM is a chronic condition caused by reduced insulin secretion and increased insulin resistance." (PMID 38152822, 2023). "What is more, PD caused a statistically significant decrease in glucose, insulin, Homeostatic Model Assessment—Insulin Resistance (HOMA-IR) and glycated hemoglobin (HbA1c) in the short term (up to 6 months)—contrary to various CDs, which caused only a significant decrease in HbA1c." (PMID 37836439, 2023). "During puberty, with an increment in GH and IGF-1 levels, the sex hormones have a significant impact on the linear growth and enhance the intensity of fluctuation in GH; this rise in GH is higher in T1DM children and is considered the cause of high insulin requirement and insulin resistance." (PMID 37859903, 2023). "A generally accepted view is that insulin resistance associated with T2D is caused by defects at one or several levels of the insulin-signaling cascade, for example, in skeletal muscles, adipose tissue, and liver, that quantitatively constitute the bulk of the insulin-responsive tissues." (PMID 37680885, 2023). "Type 2 diabetes is associated with obesity and occurs as a consequence of insulin resistance, which emerges when three major insulin-sensitive tissues (skeletal muscle, liver, and adipose tissue) can not respond well to insulin and can not effectively take up glucose from blood." (PMID 36119080, 2022). "This means LECT2 plays an important role in the regulation of insulin sensitivity, and it may provide a novel perspective for the therapy of obesity‐associated insulin resistance." (PMID 35656863, 2022). "Considering that weight gain is one of the main factors of insulin resistance, we showed that oral administration of garlic extract for two months caused simultaneously a significant decrease in body weight and an improvement of insulin sensitivity." (PMID 36352899, 2022). "Furthermore, these associations are very likely to be underpinned by insulin resistance as the genetic risk score for WHRadjBMI was also shown to be strongly associated with elevated fasting insulin, higher TGs, and lower HDL cholesterol." (PMID 34875679, 2022). "However, a meta-analysis of 76,558 non-diabetic populations of European descent found that the G allele at IGF1 rs35767 was associated with increased fasting insulin levels and insulin resistance (HOMA-IR)." (PMID 35094288, 2022). "Insulin resistance is thus the cause of inflammation (increase in various inflammatory factors) and depends on the structure of the intestinal microbiota, which has a significant influence on insulin metabolism." (PMID 36013366, 2022). "Another contribution of insulin resistance to MetS is the development of hypertension caused partly by loss of insulin’s vasodilatory effect and by FFA-induced vasoconstriction due to reactive oxygen species production and subsequent scavenging of nitric oxide." (PMID 35054972, 2022). "Some studies showed that higher fasting insulin levels representing systemic insulin resistance might be associated with more significant declines in memory impairment." (PMID 35892598, 2022). "We hypothesised that MAIT cells are associated with insulin resistance in children with obesity, and affect insulin signalling through their production of IL-17." (PMID 35305128, 2022).
Insulin resistance (continued). "In addition, HOMA-IR index is a classical indirect method of assessing insulin resistance, but it is susceptible to the accuracy of insulin measurements and is poorly reproducible." (PMID 36211651, 2022). "As NAFLD is also closely linked to insulin resistance, the reduction of liver fat should improve alpha-cell insulin sensitivity and may thereby reduce fasting and postprandial GCGN release." (PMID 35662921, 2022). "As a result, inflammatory cytokines are produced more frequently, causing metabolic cells to use different signaling pathways that not only deactivate the insulin signal, causing insulin resistance, but also change the expression of proteins that aid in glucose transport." (PMID 35456284, 2022). "Moreover, the percentage of Th1 cells producing IFN-γ is positively associated with insulin resistance in obese patients, indicated by an increase of the circulating level of leptin, insulin and HOMA-IR values." (PMID 36457551, 2022). "Significant pathophysiological features of T2DM are insulin resistance accompanied by an absolute or relative deficiency in insulin secretion due to the fact of a defect in pancreatic beta-cell function, and obesity is strongly associated with insulin resistance." (PMID 36010438, 2022). "Likewise, early deficits in cerebral glucose metabolism precede the development of cognitive symptoms in insulin-resistant adults and in T2D, and systemic insulin resistance has been linked to Alzheimer’s disease (AD) and other dementias." (PMID 35798912, 2022). "In 2024, a clinical trial (NCT02193295) is expected to finish up and provide evidence on whether a small weight loss in lean, insulin-resistant offspring of type 2 diabetic patients will improve insulin resistance." (PMID 35454311, 2022). "Insulin resistance causes type-2 diabetes, which mediates increased glucose synthesis in the liver and decreases glucose intake in muscle and adipose tissue at a certain insulin level." (PMID 35207564, 2022). "In obese people, chemerin which is positively associated with insulin, and low-density lipoprotein cholesterol, may have a role in insulin resistance and oxidative stress." (PMID 36290249, 2022). "Insulin resistance and poor insulin sensitivity are hallmark features of T2DM and NAFLD." (PMID 35765060, 2022). "IL-6 downregulates insulin signaling and causes insulin resistance in adipocytes." (PMID 36339572, 2022). "ROS can interfere with the insulin signal transduction pathway, causing insulin resistance." (PMID 35236828, 2022). "Insulin use itself may represent a more potent marker for insulin-resistance, and hence a better predictor of risk for stroke or progressive small vessel ischemic disease than HbA1c." (PMID 38983558, 2022). "Studies suggest that CDKAL1 polymorphisms may modulate insulin secretion or be related to insulin resistance." (PMID 36183068, 2022). "Insulin resistance may result not only from β-cell dysfunction or glucose disposal impairment but can also be caused by a reduction in insulin-mediated thermogenesis." (PMID 35757435, 2022). "Moreover, longer duration is linked to a reduction in insulin secretion or excessive insulin resistance in people living with T2DM." (PMID 35114950, 2022). "Adiposity is strongly linked to insulin resistance, and therefore weight loss induced by the aerobic exercise programme (indicated through a reduction in BMI) may also increase insulin sensitivity." (PMID 35930075, 2022). "Since Ser307 phosphorylation of IRS-1 is linked to cytokine-mediated insulin resistance, it may explain the blunted effect of insulin on Akt phosphorylation and on the reduction in FFA release in OSM-treated adipocytes." (PMID 35531859, 2022). "The results reveal that SYTZD caused an improvement in insulin sensitivity and insulin resistance." (PMID 36506575, 2022). "Multiple studies have linked VF to impaired insulin signalling and insulin resistance (IR)." (PMID 35843982, 2022).